AR (androgen receptor)
Diseases named in the same sentence as AR in open-access papers (continued):
Sharing a sentence is not in itself a finding about the gene and the disease.
prostate carcinoma (continued). "AR ChIP-seq differential binding analysis yielded HOXB13 motif as selectively enriched in resistant tissue, suggesting a role of HOXB13 in resistant prostate cancer as found by others." (PMID 26412853, 2015). "The relationship between prostate cancer outcome and AR levels in stroma and epithelium was investigated by AR immunohistochemistry on 64 patient-matched BPH and prostate cancer samples in patients of median age 87 years." (PMID 25965833, 2015). "Unexpectedly, we observed a physical interaction between CXCR7-SBP and AR in C7-SBP cells, and functional interactions between CXCR7 and AR in LNCaP prostate-cancer cells." (PMID 25884570, 2015). "Sorafenib has been shown to act directly on human prostate cancer cells decreasing cellular proliferation and inducing apoptosis through the downregulation of AKT and androgen receptor pathways." (PMID 25953027, 2015). "The AR plays a major role in all stages of prostate cancer development and progression, including CRPC, thus it is important to determine the mechanisms involved including the impact of AR co-regulators." (PMID 26176602, 2015). "It has been reported that inhibition of the PI3K pathway increased AR protein levels and its target gene activity in PTEN-negative prostate cancers." (PMID 26506516, 2015). "The chaperoning complex is a potentially important therapeutic target in advanced prostate cancer, given the significance of HSP client proteins including growth factors and the AR." (PMID 25241147, 2015). "Functional cross talks between the AR and HER2 signalling pathways in MDA-MB-453 and SUM-190 breast cancer cell have considerable similarities to prostate cancer cell lines suggesting an oncogenic potential of AR in ER–/AR+ breast cancers." (PMID 25781993, 2015). "As expected, multiple motifs of transcription factors involved in prostate cancer pathobiology were found, including ERG, AR, and its pioneer factor FOXA1 (Table EV1)." (PMID 26412853, 2015). "Interestingly, ASCT2 expression significantly increased in patients with recurrent prostate cancer (p < 0.001), indicating either re‐activation of androgen receptor signalling or that other signalling pathways might up‐regulate ASCT2 expression upon disease recurrence." (PMID 25693838, 2015). "In prostate cancer cellsexpressing the androgen receptor (AR), PARP1 is recruited to the sites of ARlocalization and stimulates AR activity." (PMID 26483957, 2015). "Androgen receptor (AR) and MNK activated eIF4E signaling promotes the development and progression of prostate cancer (PCa)." (PMID 25605250, 2015). "In the TRAMP transgenic model of spontaneous prostate cancer, MVA-TWIST/TRICOM alone significantly improved survival, and when combined with the androgen receptor antagonist enzalutamide, the vaccine further improved survival." (PMID 26317648, 2015). "In summary, our study identifies for the first time novel retinamides that can simultaneously inhibit both AR signaling and MNK mediated eIF4E activation in prostate cancer cells." (PMID 25605250, 2015). "In contrast, others have reported that activated AR promoted EMT through decreased E-cadherin expression and that prostate cancer cells underwent EMT in response to androgens." (PMID 25821081, 2015). "Given that β-catenin interacts with AR or TCF to activate AR or Wnt/β-catenin-responsive transcription, respectively, in prostate cancer, we examined the β-catenin occupancy on AR and TCF binding sites using chromatin immunoprecipitation (ChIP) assays." (PMID 26509262, 2015). "Androgen receptor (AR) signalling and the PI3K pathway mediate survival signals in prostate cancer, and have been shown to regulate each other by reciprocal negative feedback, such that inhibition of one activates the other." (PMID 26501081, 2015). "Indeed, stromal AR may be pro-proliferative in early prostate cancer; exogenous tumors in mice grow larger when associated with AR sensitive stroma, and are inhibited by stroma lacking AR." (PMID 25965833, 2015).
prostate carcinoma (continued). "In fact, by catalyzing histone H3 Thr11 phosphorylation in response to AR activation, PRK1 has been dubbed a “gate-keeper” of androgen-induced transcriptional activation and, therefore, of androgen-driven prostate cancer." (PMID 26296974, 2015). "Given the critical role of FKBP52 in AR signaling in vitro and in vivo, FKBP52 has emerged as an attractive target for the treatment of prostate cancer." (PMID 26207810, 2015). "Interaction between the PI3K and AR pathways has been well studied and in fact reciprocal feedback between the two pathways in PTEN-deleted prostate cancer has been reported, indicating the importance of targeting both pathways in PTEN-deleted disease." (PMID 26509262, 2015). "Given that prostate cancer is characterized by AR-driven SENP1 expression, it is possible that drugs targeting SENP1, possibly in combination with anti-androgenic therapy, will also be effective in prostate cancer." (PMID 26202067, 2015). "Future studies will need to include overexpression of HES5 in prostate cancer cells to establish the direct consequences on HES6 and AR signalling, as well as the phenotypic consequences of bypassing HES5 silencing." (PMID 25560400, 2015). "Since AR plays a critical role in proliferation and survival of PCa cells and CaM regulates AR activity, we tested the effect of HBC on proliferation of prostate cancer cells that are AR-positive and depend on AR for proliferation (LNCaP cells)." (PMID 25704883, 2015). "Based on the special role of AR in prostate cancer and the difference of CX43 expression in prostate cancer and other tumors, we examined the effect of AR pathway on CX43." (PMID 26491675, 2015). "In breast cancer, AR is positively correlated with HER2 overexpression and reciprocal activation between AR and HER2 occurs in both breast and prostate cancer cell lines." (PMID 26554309, 2015). "Collectively, these results suggest that novel retinamides that function as dual inhibitors of AR and MNK signaling in androgen-dependent and castration-resistant PCa have great potential as novel therapeutics for treatment of advanced prostate cancer." (PMID 25605250, 2015). "This additive interaction suggests that AR and CXCR7 act on separate unrelated processes to reciprocally regulate their protein expression in LNCaP prostate-cancer cells." (PMID 25884570, 2015). "To analyze global transcriptional function, we then extensively mapped RUNX1 binding sites in the prostate cancer genome and identified RUNX1 is recruited to AR binding sites by direct interaction with AR." (PMID 25537508, 2015). "Both ligands repressed DHT (1nM)-dependent induction of ARE-regulated reporters in LNCaP prostate cancer cells that express endogenous ARs and in PC3 and HEK293T cells transfected with an AR expression vector." (PMID 26332122, 2015). "As androgen activation of stably expressed AR has been shown to inhibit proliferation of PC-3 prostate cancer cells, we investigated the extent to which AR regulates cell cycle progression and cyclin D-CDK4/6 complexes in PC3-Lenti-AR." (PMID 26372468, 2015). "A connection between androgen/AR/p21WAF1/CIP1/cyclinD1 has been reported and this connection is proposed to be important for prostate cancer progression." (PMID 26622945, 2015). "In prostate cancer cell line, the expression of CTBP1-AS is regulated by binding of androgen receptor at the 5′ of its TSS." (PMID 25883552, 2015). "In prostate cancer, GATA2 plays a crucial role in mediating androgen receptor (AR) expression, as well as in site-specific AR recruitment facilitating AR target gene expression." (PMID 26287967, 2015). "We found that in prostate cancer cells, OTUB1 has the capacity to modulate cell invasion of both AR+ and AR- cells in a manner that seems to be dependent on the presence of an intact active site." (PMID 25623341, 2015).
prostate carcinoma (continued). "The VCaP cells used in our studies are slow-growing, androgen-sensitive, and possess a wild-type androgen receptor, making them a bit closer to the nature of the indolent and [18F]FDG-PET “invisible” prostate carcinomas." (PMID 25561013, 2015). "While the functional consequences of this remain to be explored, the implication of both AR and ERG oncogenenic signalling axes provides further weight for the importance of the HES transcriptional network in prostate cancer." (PMID 25560400, 2015). "This concept is supported by studies demonstrating that the growth of cell line and xenograft models of AR-positive TNBC is inhibited by treatment with the AR antagonist bicalutamide, a drug historically developed to treat men with prostate cancer." (PMID 26554309, 2015). "The majority of prostate cancers (PCa) and Castrate Resistant Prostate Cancers (CRPC) have functional AR, which continues to drive the expression of AR-dependent cell proliferative genes and hence the tumor growth despite of low level of systemic androgens." (PMID 26008968, 2015). "We found that AR/p52-02 markedly inhibited growth of both castration-resistant C4-2 (IC50 ∼6 μM) and parental androgen-dependent LNCaP (IC50 ∼4 μM) human prostate cancer cells under low androgen conditions." (PMID 26622945, 2015). "As a part of our studies of androgen receptor (AR) function and mechanisms of CRPC progression, we recently characterized four new murine prostate cancer cell lines derived from either hormone intact (E4, E8) or castrated (cE1, cE2) Pten null mutant mice." (PMID 26196517, 2015). "MTR1 had been related to antiproliferative response of prostate cancer cells to MLT, which leads to the downregulation of activated AR signaling and upregulation of p27kipi in 22Rv1 cells." (PMID 26295055, 2015). "The AR and its fusion-gene target TMPRSS2-ERG are important regulators of oncogenic pathways in prostate cancer cells." (PMID 26035357, 2015). "To assess if Usp12 additionally controls AR phosphorylation and activity by regulating pAkt levels, we overexpressed AR and Usp12 in the PC3 prostate cancer cell line and assessed the phosphorylation status of the receptor." (PMID 25216524, 2014). "This phosphorylation event reduces the interaction between AR and CHIP leading to AR stabilization and enhanced growth of prostate cancer cells even at very low levels of androgen." (PMID 24868554, 2014). "Our findings characterize PKG as a novel regulator of AR-mediated transcription by enhancing AR cofactor p44/WDR77's function, which provide a novel mechanism for the growth regulation of prostate cancer cells by the androgen signaling." (PMID 23755100, 2014). "In prostate cancer, miR-205 functions as a tumor suppressor through downregulation of multiple targets like BCL2, protein kinase C epsilon, and androgen receptor." (PMID 25243154, 2014). "After treatment with BBR, prostate cancer cells decrease their proliferation by a direct activation of AMPK, contributing to the degradation of AR and leading to apoptosis." (PMID 25153862, 2014). "In prostate cancer, YY1 physically interacts with androgen receptor (AR), which is required for the optimal transcriptional activity of AR in promoting the transcription of the prostate-specific antigen (PSA), a protein enhancing cell migration and metastasis." (PMID 24674326, 2014). "Several other genetic lesions have been identified in prostate cancer, such as SRD5A (steroid-5-alpha-reductase alpha polypeptide), androgen receptor, estrogen receptor-β, E-cadherin, and toll-like receptors." (PMID 25045667, 2014). "To further address the potential role of MID1 in prostate cancer, we evaluated MID1 and AR expression levels by immunohistochemistry (IHC) in prostate cancer specimens." (PMID 24913494, 2014).
prostate carcinoma (continued). "A recent siRNA screen identified AKT1 as a target that impaired the growth of AR + prostate cancer cell lines, consistent with the PI3K pathway playing an essential role in survival of AR-dependent cells." (PMID 25103565, 2014). "Among these modules, transcription Androgen Receptor (AR) nuclear signaling and Epidermal Growth Factor Receptor (EGFR) signalling pathway were shown to be the pathway targets for prostate cancer progression." (PMID 25080090, 2014). "Reports on associations between the GGN repeat and AR function are limited and inconsistent, with one study describing a positive association in a cohort of men with prostate cancer, whereas another study in young men could not find an association between the GGN repeat and serum T levels." (PMID 24465978, 2014). "Concerning on pathway enrichment analysis, Transcription Androgen Receptor (AR) nuclear signaling and Epidermal Growth Factor Receptor (EGFR) signalling pathway were clearly shown to be the pathway targets for prostate cancer progression." (PMID 25080090, 2014). "The effects of GEN-mediated HDAC6 down-regulation on AR-signaling were mimicked by HDAC6 siRNA, thus confirming the importance of this mechanism for prostate cancer preventive potential of GEN." (PMID 25322458, 2014). "It is important to notice that associations with PRDX1 and the endocrine system have been recently described in prostate cancer, including effects of PRDX1 on androgen receptor activity and the response to anti-androgen therapies." (PMID 25011585, 2014). "The growth of advanced prostate cancer (both castration-sensitive prostate cancer (CSPC) and castration-resistant prostate cancer (CRPC)) depends on androgen receptor signaling." (PMID 25296973, 2014). "Recent global gene expression studies of prostate cancer and triple-negative breast cancer have shown that high FOXA1 expression, which correlates positively with AR level, promotes tumor proliferation." (PMID 24512546, 2014). "It is of note that it is also recently reported that PCAT18 is a highly prostate-specific transcript, upregulated in prostate cancer, and that the expression of PCAT18 is induced by AR signaling." (PMID 25243154, 2014). "In prostate cancer, KLF5 was found to become expressed downstream of androgen receptor (AR) signaling." (PMID 24429391, 2014). "The precise role of AR axis in CRPC and prostate cancer metastasis has been well recognized in the last decades." (PMID 24618337, 2014). "In prostate cancer, membrane receptor tyrosine kinases (RTK) have been shown to modulate the AR expression." (PMID 24779793, 2014). "We used androgen sensitive prostate cancer cells that progressed to ADT and AR antagonist Casodex (CDX) resistance upon androgen withdrawal and treatment with CDX." (PMID 24387052, 2014). "The androgen receptor (AR) is activated by the binding of testosterone or its physiologically active metabolite, 5α-dihydrotestosterone (DHT) and is involved in prostate cancer initiation and metastasis." (PMID 24275493, 2014). "Expressing prostate cancer cells pretreated with celastrol was reported to dose-dependently inhibit TMPRSS2-ERG fusion, AR and AR3 gene expression." (PMID 24739220, 2014). "A loss of expression of AR was noted in these cells (data not shown), which supports the report showing an inverse relationship between expression of AR and EGFR in prostate cancer patients." (PMID 24387052, 2014). "Plasmids incorporating the CAT gene under the control of an AR responsive promoter and wild-type AR were co-expressed with either empty vector, wild-type MID1 or mutant MID1 expression vectors in the AR-negative prostate cancer cell line PC-3." (PMID 24913494, 2014).
prostate carcinoma (continued). "Novel endocrine treatments targeting the AR signaling axis, including abiraterone acetate and MDV3100, have recently shown clinical promise for advanced prostate cancer, particularly in the second-line therapeutic setting." (PMID 23152004, 2013). "However, the origin of prostate cancer from basal cells was recently suggested by Witte and coworkers who reported that basal cells isolated from primary benign human prostate tissue and transfected with AR and AKT/ERG were able to establish prostate tumors in NSG mice." (PMID 23358633, 2013). "The 22Rv1 cell line is androgen-responsive and originally derived from the relapsed CWR22 xenograft, expressing both the androgen receptor and PSA, thus representing a model of advanced prostate cancer." (PMID 23675504, 2013). "It has been amply documented that AR, PI3K/Akt, and ERK pathways are important features contributing to uncontrolled prostate cancer cell growth and survival." (PMID 23566222, 2013). "Therapy disrupting AR-Sp1 complexes and thereby suppressing VEGF would be expected to limit angiogenesis and maintain the indolent form of prostate cancer." (PMID 23369005, 2013). "The significant positive correlation between PA1 and ERs or AR, strongly suggested that further investigational study on PA1 expression in the other hormone related cancers such as prostate cancer, ovarian cancer and endometrial cancer." (PMID 24260416, 2013). "We characterized AR, MYC, and TMRPSS2-ERG expression in two established primary prostate cancer xenograft models: the castration-resistant LuCaP 35CR model (formerly named LuCaP 35V;) and the neuroendocrine prostate cancer model LuCaP 145.2." (PMID 24293458, 2013). "Combined with the detection of other critical genomic biomarkers for prostate cancer such as ERG, androgen receptor, and MYC, the evaluation of PTEN genomic status has proven to be invaluable for patient stratification and management." (PMID 24062990, 2013). "For example, evidence for cooperation between AR and NCOA2 amplifications on 8q13.3 in early prostate cancer was reported." (PMID 23561577, 2013). "A crosstalk between AR and EGFR was previously observed in human hormone-dependent prostate cancer-derived LNCaP cells." (PMID 24130806, 2013). "A well-known gene regulated by AR is prostate specific antigen (PSA), which currently is used as a biomarker for prostate cancer (PCa)." (PMID 23863692, 2013). "In C4-2 castration-resistance prostate cancer cells, HDAC6 seemed to regulate the androgen receptor (AR), also through deacetylation of HSP90." (PMID 23644884, 2013). "In order to determine whether N-linked glycosylation alters AR activity, we evaluated the effect of tunicamycin on the expression of Kallikrein 3 (KLK3), which is a direct AR target protein, and also a well-characterized biomarker for prostate cancer and known glycoprotein." (PMID 23724116, 2013). "In both cases, as with other prostate cancer treatments, disease progression most frequently correlates with a rise in PSA levels, indicating reactivation of the androgen receptor." (PMID 23667504, 2013). "We also show that VK2 treatment reduces androgen receptor expression and PSA secretion in androgen-dependent prostate cancer cells." (PMID 24062781, 2013). "In prostate cancer, FHL2 acts as a coactivator, shifts to the nucleus and subsequently activates FHL2- and androgen receptor-dependent genes." (PMID 23311569, 2013). "HR prostate cancer (LNCaP-HR and TRAMP-HR) had higher levels of IL-6, more activated STAT3 and AR compared to hormone sensitive prostate cancer cells (LNCaP and TRAMP-C1) shown in our previous and the present study." (PMID 23806095, 2013).